ADRM1 (ADRM1 26S proteasome ubiquitin receptor)
Description:
Component of the 26S proteasome, a multiprotein complex involved in the ATP-dependent degradation of ubiquitinated proteins. This complex plays a key role in the maintenance of protein homeostasis by removing misfolded or damaged proteins, which could impair cellular functions, and by removing proteins whose functions are no longer required. Therefore, the proteasome participates in numerous cellular processes, including cell cycle progression, apoptosis, or DNA damage repair. Within the complex, functions as a proteasomal ubiquitin receptor. Engages and activates 19S-associated deubiquitinases UCHL5 and PSMD14 during protein degradation. UCHL5 reversibly associate with the 19S regulatory particle whereas PSMD14 is an intrinsic subunit of the proteasome lid subcomplex.
Synonyms: Gp110; ARM-1; Rpn13; ARM1; PSMD16
Tractability: Small molecule: an approved drug acts on it; a structure with a bound ligand is known; a high-quality ligand is known. Antibody: its Gene Ontology location is reachable by antibodies, with high confidence. PROTAC: it is named in the literature on targeted protein degradation; UniProt records ubiquitination sites on it; ubiquitination databases record sites on it; its protein half-life has been measured.
Gene: Protein-coding gene on chromosome 20 (62,302,066 to 62,308,867, forward strand). Ensembl gene ENSG00000130706.
Subcellular location: Cytoplasm; Nucleus
Subcellular location (Human Protein Atlas): Cytosol; Nucleoplasm; Plasma membrane
Pathways (Reactome):
Immune System: AMPK-induced ERAD and lysosome mediated degradation of PD-L1(CD274); Activation of NF-kappaB in B cells; Antigen processing: Ubiquitination & Proteasome degradation; CLEC7A (Dectin-1) signaling; Cross-presentation of soluble exogenous antigens (endosomes); Dectin-1 mediated noncanonical NF-kB signaling; Downstream TCR signaling; ER-Phagosome pathway; FCERI mediated NF-kB activation; GSK3B-mediated proteasomal degradation of PD-L1(CD274); Interleukin-1 signaling; NIK-->noncanonical NF-kB signaling; SPOP-mediated proteasomal degradation of PD-L1(CD274); TNFR2 non-canonical NF-kB pathway
Cell Cycle: APC/C:Cdc20 mediated degradation of Securin; APC/C:Cdh1 mediated degradation of Cdc20 and other APC/C:Cdh1 targeted proteins in late mitosis/early G1; Autodegradation of Cdh1 by Cdh1:APC/C; Autodegradation of the E3 ubiquitin ligase COP1; Cdc20:Phospho-APC/C mediated degradation of Cyclin A; FBXL7 down-regulates AURKA during mitotic entry and in early mitosis; G2/M Checkpoints; SCF(Skp2)-mediated degradation of p27/p21; SCF-beta-TrCP mediated degradation of Emi1; Separation of Sister Chromatids; The role of GTSE1 in G2/M progression after G2 checkpoint; Ubiquitin-Mediated Degradation of Phosphorylated Cdc25A; Ubiquitin-dependent degradation of Cyclin D
Signal Transduction: Asymmetric localization of PCP proteins; Degradation of AXIN; Degradation of DVL; Degradation of GLI1 by the proteasome; Degradation of GLI2 by the proteasome; Degradation of beta-catenin by the destruction complex; GLI3 is processed to GLI3R by the proteasome; Hedgehog 'on' state; Hedgehog ligand biogenesis; MAPK6/MAPK4 signaling; Negative regulation of NOTCH4 signaling; Regulation of PTEN stability and activity; Regulation of RAS by GAPs
and 27 more pathways
Gene Ontology:
Molecular function: endopeptidase activator activity; molecular function inhibitor activity; protease binding; proteasome binding; protein binding
Biological process: proteasome assembly; transcription elongation by RNA polymerase II; cellular response to type I interferon; proteasomal protein catabolic process; proteasome-mediated ubiquitin-dependent protein catabolic process; regulation of proteasomal protein catabolic process; response to oxidative stress
Cellular component: cytoplasm; cytosol; nucleoplasm; nucleus; proteasome complex; proteasome regulatory particle, lid subcomplex; synaptic vesicle
Genetic constraint (gnomAD): Loss-of-function variants: 2 observed, 33.48 expected, observed/expected ratio (o/e) 0.0597, 90% interval 0.023 to 0.19. The upper end of that interval is the gene's LOEUF score, 0.19, which puts it in group 1 of 6, group 1 being the genes least tolerant of losing a copy. Missense variants: 436 observed, 512.9 expected, observed/expected ratio (o/e) 0.85, 90% interval 0.79 to 0.92. Synonymous variants: 271 observed, 225.38 expected, observed/expected ratio (o/e) 1.2, 90% interval 1.09 to 1.33.
Homologues: Orthologues: chimpanzee ADRM1 (100% identical), guinea pig ADRM1 (97% identical), pig ADRM1 (97% identical), mouse Adrm1 (82% identical), mouse Adrm1b (81% identical), dog ADRM1 (80% identical), rat Adrm1 (79% identical), zebrafish adrm1 (76% identical), Drosophila melanogaster Rpn13 (42% identical), Caenorhabditis elegans rpn-13 (32% identical), Drosophila melanogaster Rpn13R (26% identical).
Diseases named in the same sentence as ADRM1 in open-access papers:
ADRM1 is named in the same sentence as 40 diseases in open-access papers, as found by Europe PMC text mining. Sharing a sentence is not in itself a finding about the gene and the disease. The quoted sentences say what the papers report.
ovarian carcinoma (13 papers, 2009 to 2024). A malignant neoplasm originating from the surface ovarian epithelium. "The 19S RP subunit protein RPN13, which is encoded by ADRM1, has emerged as a promising target for the treatment of ovarian cancer and several other types of solid and liquid tumors." (PMID 37315065, 2023). "Amplification of ADRM1 is most common in ovarian cancer and is associated with shorter time to recurrence and overall survival, although it does not predict sensitivity to RA190 in cell lines." (PMID 31940398, 2020). "ADRM1 mRNA overexpression is associated with chromosome 20q13 amplification, but was not obviously associated with concurrent protein level changes in ovarian cancer cell lines." (PMID 28784174, 2017). "Because ADRM1 is a proteasomal ubiquitin receptor, future work may focus on the susceptibility to proteasome inhibitors in ADRM1-amplified ovarian cancer." (PMID 23377018, 2013). "In the tumor microenvironment of ovarian cancer, RPN13/ADRM1 inhibitors can reverse immunosuppression which effects attributed to myeloid-derived suppressor cells." (PMID 37684377, 2023). "Overexpression of ADRM1 is an early event in the genesis of ovarian cancer, and correlates significantly with shorter time to recurrence and overall survival, as well as higher stage disease and recurrence." (PMID 34506530, 2021). "Nevertheless, bis-benzylidine piperidone RA190, an ADRM1 Inhibitor, has the effect of reduced growth of multiple myeloma and ovarian cancer xenografts." (PMID 34724890, 2021). "Ovarian cancer is a promising target because RPN13, which is encoded by ADRM1, is consistently over-expressed in high grade serous carcinoma, and this occurs in the precursor lesion." (PMID 31940398, 2020). "Ectopic ADRM1 overexpression in cell lines increases proliferation, migration, and growth in soft agar, and knock-down of ADRM1 expression results in apoptosis, and it has been suggested as an oncogene and novel therapeutic target for ovarian cancer." (PMID 31940398, 2020). "From analysis of TCGA data it is apparent that ovarian cancer has a higher frequency of ADRM1 amplification (~8–15%) as compared to other cancers and amplification is moderately correlated with elevated mRNA expression level (Pearson coefficient = 0.538)." (PMID 28784174, 2017). "Further, in vitro overexpression of ADRM1 has led to increase in proliferation and migration of transfected ovarian cancer cell line, ES2, and has been correlated to shortened survival and more rapid relapse." (PMID 28784174, 2017). "Next, we utilized the ADRM1 mRNA CISH assay to probe adjacent slides from the samples of 7 ovarian cancer patients with matched STICs, normal fallopian tube epithelium, and the additional samples from 13 HGSC patients." (PMID 28784174, 2017). "Conversely, using ectopic over expression of ADRM1 in ES2 cells to examine its biologic function in ovarian cancer cells, they observe that ADRM1 over-expression increases cell proliferation, migration and growth in soft agar." (PMID 28784174, 2017). "Here, we sought to determine if RPN13 is available as a target in precursors of ovarian/fallopian tube cancer as well as all advanced cases, and the impact of increased ADRM1 gene copy number on sensitivity of ovarian cancer to RA190." (PMID 28784174, 2017). "The bis-benzylidine piperidone RA190 binds to the ubiquitin receptor RPN13/ADRM1 on the 19S regulatory particle of the proteasome and directly kills ovarian cancer cells by triggering proteotoxic stress." (PMID 27655678, 2016). "The results indicate that amplified ADRM1 is involved in cell proliferation, migration and survival in ovarian cancer cells, supporting a role as an oncogene and novel therapeutic target for ovarian cancer." (PMID 23377018, 2013). "Array-CGH and microarray expression of ovarian cancer cell lines provided evidence consistent with primary tumor data that ADRM1 is a 20q13 amplification target." (PMID 23377018, 2013).
ovarian carcinoma (continued). "Herein, we confirm the ADRM1 amplicon in a second ovarian cancer cohort and define a minimally amplified region of 262 KB encompassing seven genes." (PMID 23377018, 2013). "Recently, we showed that among 20q13-amplified genes in ovarian cancer, ADRM1 overexpression was the most highly correlated with amplification and was significantly upregulated with respect to stage, recurrence, and metastasis." (PMID 23377018, 2013). "We have shown that amplification in ovarian cancer tumors is a major mechanism of up-regulation of ADRM1 and that its expression increases with tumor stage and recurrence." (PMID 23377018, 2013). "The gene encoding RPN13, ADRM1, has been proposed as an oncogene in ovarian cancer." (PMID 38990850, 2024). "ADRM1 is overexpressed in multiple myeloma, ovarian cancer, colon cancer and gastric cancer." (PMID 31798765, 2019). "The role ADRM1 plays in ovarian cancer is unknown but it has been shown to be upregulated in metastatic tumor cells, and its overexpression increased the propensity of cells to engage in cell-cell interactions." (PMID 23377018, 2013). "Amplification of 20q13 may be particularly heterogeneous as AURKA, TGIF2, PTPN1 and ZNF217, and ADRM1, and other genes, have been cited as drivers of 20q13 amplification in ovarian cancer." (PMID 19419571, 2009). "Furthermore, ADRM1 also encodes RPN13, a critical ubiquitin receptor, and the application of inhibitors targeting the ADRM1/RPN13 interaction has been shown exert a substantial restraining effect on the amplification of ovarian cancer cell." (PMID 37684377, 2023). "Indeed, ADRM1 has been proposed as a driver oncogene in ovarian cancer." (PMID 37315065, 2023). "Thus this study provides evidence that ADRM1 plays a role in ADRM1-amplified ovarian cancer." (PMID 23377018, 2013). "ADRM1 mRNA and RPN13 were ubiquitously and robustly expressed in ovarian carcinoma tissue and cell lines." (PMID 28784174, 2017). "Among these, ovarian cancer cell line OAW42 was found to be amplified and had the highest level of overexpression and was used as a model for knock-down of expression of ADRM1 in ADRM1-amplified ovarian cancer." (PMID 23377018, 2013). "Overexpression of ADRM1 mRNA and /or RPN13 was reported in many types of malignancy, including multiple myeloma, diffuse large B-cell lymphoma, gastric cancer, ovarian cancer, and intrahepatic cholangiocarcinoma and high expression of RPN13 correlated with poor prognosis." (PMID 32375699, 2020). "Patient tumor tissue samples as well as ovarian cancer cell lines show relatively consistent protein levels regardless of ADRM1 mRNA expression levels suggesting that RPN13 expression is heavily post-transcriptionally regulated." (PMID 28784174, 2017). "Amplification of ADRM1 and sensitivity to RA190 were determined in ovarian cancer cell lines." (PMID 28784174, 2017). "However, regardless of ADRM1 amplification status the RPN13 protein levels are relatively consistent across ovarian cancer cell lines." (PMID 28784174, 2017). "Ovarian cancer cell lines are sensitive to RA190 regardless of whether the ADRM1 gene is amplified." (PMID 28784174, 2017). "Since ADRM1 amplification was also not correlated with sensitivity to RA190, this suggests it can be tested against ovarian cancer regardless of increased ADRM1 copy number." (PMID 28784174, 2017).
multiple myeloma (8 papers, 2015 to 2025). "ADRM1 inhibition through the inhibitor RA190 induces apoptosis in multiple myeloma cell lines, suggesting that it might be a good target for multiple myeloma treatment." (PMID 31798765, 2019). "While the proteasome inhibitors bortezomib and carfilzomib licensed for treatment of relapsed multiple myeloma act by inhibiting the 20S catalytic core, RA190 irreversibly binds to the ubiquitin receptor RPN13/ADRM1 on the 19S regulatory cap of the 26S proteasome." (PMID 27655678, 2016).
gastric cancer (5 papers, 2019 to 2024). A primary or metastatic malignant neoplasm involving the stomach. "YY1 directly binds to CCDC43 and ADRM1 gene promoters, leading to their overexpression, and subsequently the aggressiveness of gastric cancer." (PMID 35747809, 2022). "ADRM1 gene amplification is a candidate driver for metastatic gastric cancers." (PMID 38322112, 2024). "Recent publications reveal that ADRM1 transcription is consistently elevated in ovarian, colorectal and gastric cancer tissues, and knockdown of ADRM1 expression in both human colon carcinoma and gastric cancer cell lines suppress cell migration and proliferation, and induces cell apoptosis." (PMID 32811556, 2020).
hepatocellular carcinoma (4 papers, 2015 to 2024). A malignant tumor that arises from hepatocytes. "Given the potential oncogenic function of ADRM1 in hepatocellular carcinoma, our objective was to investigate its correlation with vital immune checkpoints that contribute to the evasion of tumor immunity." (PMID 38890391, 2024). "Based on this, we studied the relationship between the expression of ADRM1 in hepatocellular carcinoma and immune cell infiltration, immune cell labeling, and immune test sites." (PMID 38890391, 2024). "Simultaneously, through the detection of ADRM1 upstream of miRNAs in hepatocellular carcinoma, its function can be regulated." (PMID 38890391, 2024). "It is suggested that ADRM1 plays a key role in the occurrence and development of hepatocellular carcinoma." (PMID 38890391, 2024). "In hepatocellular carcinoma tissues, miR-891a-5p regulates ADRM1." (PMID 38890391, 2024). "ADRM1 is an integral plasma membrane protein that promotes cell adhesion, which has been shown to be induced in hepatocellular carcinoma (HCC)." (PMID 25901992, 2015).
bladder cancer (2 papers, 2022 to 2023). "Adhesion-regulating molecule 1 (ADRM1) has been implicated in tumor development, yet its specific role in bladder cancer (BC) remains undefined." (PMID 37684377, 2023). "Bioinformatic database screening for bladder cancer followed by gene co-expression network analysis revealed six new genes (PPARD, CST4, CSNK1E, PTPN14, ETV6, and ADRM1) and several new miRNAs, including miR-124, as drivers in the development and progression of bladder cancer." (PMID 36362406, 2022).
breast carcinoma (2 papers, 2013 to 2023). "Considering the previously observed elevation of ADRM1 mRNA in breast cancer (BC) patients, we extended our investigation to evaluate ADRM1 protein expression." (PMID 37684377, 2023). "Genes reported in Perou’s breast cancer intrinsic genes list, including WWP1, TECA3, and ADRM1, were also differentially expressed between ER-positive and -negative breast cancers." (PMID 24098497, 2013).
glioblastoma (2 papers, 2019 to 2024). The most malignant astrocytic tumor (WHO grade IV). "TMZ treatment causes the dissociation of HDAC8 from ADRM1 in TMZ-sensitive U87 glioblastoma cells." (PMID 31798765, 2019).
liver cancer (2 papers, 2024). An epithelial or non-epithelial malignant neoplasm that arises from the liver. "ADRM1 is highly expressed in tumors and is closely associated with the prognosis of patients with liver cancer." (PMID 38890391, 2024). "Prognostically, high ADRM1 mRNA level was associated with a poor prognosis in liver cancer patients." (PMID 39075049, 2024). "We used R software to analyze the correlation between ADRM1 and immune cell biomarkers in liver cancer." (PMID 38890391, 2024). "To explore the mechanism by which SIAH1 degrades ADRM1, we first determined the interaction between them in liver cancer cells." (PMID 39075049, 2024). "We validated the correlation between ADRM1 and immune cells in liver cancer cells using flow cytometry." (PMID 38890391, 2024). "The progression of liver cancer is regulated by a novel mechanism discovered in the current study involving miR-891a-5p/ADRM1 axis." (PMID 38890391, 2024). "Additional studies have shown that ADRM1 expression correlates well with various immune cell markers in liver cancer tissues." (PMID 38890391, 2024). "Proteinally, the protein of ADRM1 was higher in liver cancer tissues than normal liver tissues." (PMID 39075049, 2024). "Clinically, the mRNA of ADRM1 was high expressed in liver cancer." (PMID 39075049, 2024). "We validated the immune expression of ADRM1 in liver cancer cells using flow cytometry." (PMID 38890391, 2024). "Since UCHL5 exerts its role as a deubiquitinating enzyme through recruitment and activation by ADRM1 (adhesion regulating molecule 1), also known as Rpn13, we further explored the regulation and mechanism of action of ADRM1 on FASN in liver cancer." (PMID 39075049, 2024). "And the mRNA levels of ADRM1 and UCHL5 presented a direct correlation in normal and liver cancer specimens, as well as ADRM1 and FASN." (PMID 39075049, 2024). "In this study, we determined that ADRM1-activated UCHL5 was upregulated in liver cancer and stabilized FASN through deubiquitinating it, thereby promoting the expression of FSCN1 and filopodia formation in human liver cancer cells, as well as cell movement." (PMID 39075049, 2024). "Clinically, SIAH1 was found to be downregulated in liver cancer samples, and there was a directly negative correlation between SIAH1 and ADRM1 protein levels in normal and liver cancer specimens." (PMID 39075049, 2024).
melanoma (2 papers, 2022 to 2024). A malignant, usually aggressive tumor composed of atypical, neoplastic melanocytes.
serous carcinoma (2 papers, 2017 to 2020). "ADRM1 mRNA was quantified by RNAscope in situ hybridization and RPN13 protein detected by immunohistochemistry in high grade serous carcinoma (HGSC) of the ovary and serous tubal intraepithelial carcinoma (STIC)." (PMID 28784174, 2017).
frontotemporal dementia (1 paper, 2022). Frontotemporal dementia (FTD) comprises a group of neurodegenerative disorders, characterized by progressive changes in behavior, executive dysfunction and language impairment, as a result of degeneration of the medial prefrontal and frontoinsular cortices. "Association of SOD1 with module-1 proteins (PSMD2, ADRM1, RAD23A) were involved in ALS15-type with or without Frontotemporal dementia." (PMID 34918006, 2022).
glioma (1 paper, 2019). A benign or malignant brain and spinal cord tumor that arises from glial cells (astrocytes, oligodendrocytes, ependymal cells). "On the other hand, UCH37, the deubiquitinase activated by ADRM1, inhibits glioma cell migration and invasion, suggesting that ADRM1 inhibition could have a positive or negative effect on tumor progression, depending on the stage of the tumor." (PMID 31798765, 2019).
Hepatitis (1 paper, 2018). Inflammation of the liver. "It was proposed that Adrm1 and Isg15 might work together to induce the overexpression of Ub in ConA-induced hepatitis." (PMID 30177931, 2018).